MIR203B (microRNA 203b)
Synonyms: hsa-mir-3545; MIR3545; hsa-mir-203b
Gene: MicroRNA gene on chromosome 14 (104,117,418 to 104,117,503, reverse strand). Ensembl gene ENSG00000283165.
Gene Ontology:
Biological process: miRNA-mediated post-transcriptional gene silencing
Cellular component: RISC complex
Homologues: Orthologues: macaque mml-mir-203 (73% identical), chimpanzee ptr-mir-203 (72% identical), dog MIR203 (72% identical), guinea pig MIR203B (65% identical), mouse Mir203 (65% identical), zebrafish mir203a (63% identical), zebrafish mir203b (60% identical), tropical clawed frog xtr-mir-203 (59% identical).